FGF23 (fibroblast growth factor 23)
Diseases named in the same sentence as FGF23 in open-access papers (continued):
Sharing a sentence is not in itself a finding about the gene and the disease.
cardiovascular disease (continued). "However, vitamin D is part of a system known as mineral metabolism, which encompasses several other components, such as FGF23, PTH and phosphate that may be also related to the incidence of cardiovascular disease." (PMID 35887917, 2022). "Our data, however, showed that serum FGF23 did not predict cardiovascular disease and mortality." (PMID 26604925, 2015). "Similarly, in women with PCOS at increased risk of cardiovascular disease, assessed according to the Androgen Excess and PCOS Society consensus, FGF23 was 40% higher and vitamin D 32% lower compared with women with PCOS not at increased cardiovascular disease risk." (PMID 37251667, 2023). "Taken together our results suggest FGFR4 inhibition as a safe alternative strategy to target cardiovascular disease and chronic inflammation in patients with CKD without interrupting the necessary phosphaturic effects of FGF23." (PMID 31575945, 2019). "Thus, the dialysis patients in whom echocardiograms were performed might have had a larger cardiovascular disease burden than those not undergoing echocardiograms; however this potential confounding did not explain the relationship between FGF-23 concentrations and LV dysfunction." (PMID 23849306, 2013).
tumor (169 papers, 2008 to 2026). "This case suggests an alternative option for unresectable FGF23 transmitted tumor in the vertebrae, causing spinal myelopathy." (PMID 41717416, 2026). "Visualized results of histotopographic profiling of specific MC proteases associated with the FGF23-producing tumour demonstrated active granule secretion containing both tryptase and chymase, as well as secretion with chymase alone (Supplementary S3A–C)." (PMID 40981193, 2025). "This study is the first to analyse MCs associated with an FGF23-producing tumour, including spatial phenotyping of specific proteases, tryptase, chymase, and carboxypeptidase A3." (PMID 40981193, 2025). "Almost all cases of TIO are associated with PMT, and PMT tumor cells are able to abnormally secrete large amounts of FGF23, which acts as a key pathogenic factor leading to TIO." (PMID 40890774, 2025). "This elevated expression of FGF23 was confirmed in four UPSb tumours using RT-qPCR and, potentially, can be of diagnostic importance." (PMID 38397231, 2024). "The main symptoms of the TIO are caused by the FGF23 secreted by a tumor, leading to chronic hypophosphatemia." (PMID 39314547, 2024). "TIO is a rare paraneoplastic syndrome primarily caused by tumor overproduction of fibroblast growth factor-23 (FGF-23)." (PMID 39749027, 2024). "Serum FGF23 levels can serve as a useful diagnostic tool and a means to monitor for tumor recurrence." (PMID 39493128, 2024). "In some cases, venous sampling of FGF23 levels can be used to localize or confirm a suspected causal tumor or to distinguish between two possible lesions observed in functional imaging." (PMID 38806758, 2024). "One of the top genes upregulated in males upon tumor growth; fibroblast growth factor 23 (Fgf23) is reported to be associated to both of these processes." (PMID 37573456, 2023). "The autonomous secretion of FGF23 by tumor is the key modulator that causes urine phosphorus excretion." (PMID 37417620, 2023). "According to our data, FGF23 was expressed in the tumours, and its expression levels were higher in the high-risk group." (PMID 37388244, 2023). "Oncogenic OM, also known as tumor-induced OM (TIO), is a rare paraneoplastic syndrome associated with renal phosphate wasting in response to FGF23 secretion by a tumor." (PMID 37048797, 2023). "In some instances, venous sampling of FGF23 levels can be used to localize or confirm a suspected causative tumor or differentiate between two possible lesions seen on functional imaging." (PMID 36511653, 2023). "Tumor-induced osteomalacia (TIO), also known as oncogenic osteomalacia, is a rare paraneoplastic syndrome caused by excessive fibroblast growth factor 23 (FGF23) production by a tumor of mesenchymal origin." (PMID 35280786, 2022). "The diagnostic delay and FGF23 levels were significantly different between the different tumor sizes." (PMID 35857061, 2022). "Tumor‐induced osteomalacia (TIO)—also known as oncogenic osteomalacia—is a rare paraneoplastic syndrome caused by the overproduction of fibroblast growth factor 23 (FGF23) by a tumor." (PMID 33709632, 2021). "Within 5 days after complete resection of the tumor, there was a rapid and complete normalization of serum phosphate and FGF23 levels associated with complete resolution of the clinical picture." (PMID 27709474, 2016). "The pathogenic tumor secretes so-called phosphatonins, such as fibroblast growth factor 23 (FGF23), frizzled related protein-4, matrix extracellular phosphoglycoprotein and FGF7, which causes reduced reabsorption of phosphate in the proximal renal tubule." (PMID 25879543, 2015). "In conclusion, TIO is a paraneoplastic syndrome caused by the phosphaturic hormone FGF-23 that can be cured by removing the responsible neoplasm." (PMID 25221676, 2014). "The primary endpoint was identification of the FGF-23 concentration ratio between the venous drainage of the tumor bed and the general circulation that was diagnostic of the location of an FGF-23-secreting tumor." (PMID 21611969, 2011).
tumor (continued). "Removal of the tumor is associated with reduction in serum FGF-23 concentrations, and there is a temporal association between reduction in FGF-23 concentration and elevation in serum Pi, decrease in renal Pi wasting and increase in 1α,25(OH)2D3 concentrations." (PMID 18288501, 2008). "The classic acquired cause can include TIO, in which a small tumor secretes FGF-23." (PMID 41583152, 2025). "For example, blood draws from peripheral veins might return normal values, while measuring FGF-23 in the vein in proximity of the suspected causative tumor might produce quite different results, with elevated FGF-23 levels in the vein draining from the tumor." (PMID 37623022, 2023). "Moreover, we found that FGF23 was related to tumor size, a finding that underlines the importance of early detection of the causative tumor followed by its removal." (PMID 35857061, 2022). "Tumor-induced osteomalacia (TIO) is a rare skeletal disease caused by hypersecretion of fibroblast growth factor 23 (FGF-23) from neoplasms of mesenchymal origin; patients with TIO present with insufficiency fractures, progressive bone pain, and delayed fracture unions." (PMID 34659853, 2021). "Furthermore, FGF23 possibly contributes to a bone-like microenvironment in phosphaturic mesenchymal tumor, mixed connective tissue variant (PMTMCT), through FGFR1c/KL, inducing enhanced FGF23 production by the tumor cells and worsening TIO." (PMID 33520985, 2020). "If the causative tumor cannot be identified, the anti-FGF23 monoclonal antibody KRN23 may be therapeutically useful in TIO." (PMID 33520985, 2020). "Thus FGF23 can play a role in PCa progression as an autocrine, paracrine and/or endocrine growth factor, the relative importance of each depending on tumor FGF23 expression level, tumor site and underlying disease states in the patient." (PMID 26019137, 2015). "Venous sampling of FGF23 has been used to confirm the causative tumor preoperatively." (PMID 25181387, 2014). "Finally, the klotho gene encoding the obligate co-receptor for FGF-23 is also a putative tumour suppressor gene, further implying the link between Pi regulation and carcinogenesis." (PMID 23706176, 2013). "The consistency of FGF-23 levels declining after complete tumor resection, as observed in both our systematic review and case series, highlights its additional role as a reliable biomarker for disease activity and treatment response." (PMID 41182108, 2025). "These cytoplasmic outgrowths extended both towards neighbouring FGF23+ cells and towards other cells of the tumour microenvironment." (PMID 40981193, 2025). "Giemsa staining further revealed cells whose shape and other morphological features resembled FGF23+ cells, suggesting that they represented an atypical population within this tumour." (PMID 40981193, 2025). "Treatment relies on resection of the tumor, which leads to normalization of FGF23 and phosphate levels." (PMID 39888445, 2025). "In contrast, CD14+ monocytes and CD163+ and CD68+ macrophages predominated in the immune landscape of the FGF23-secreting tumour microenvironment, accounting for 30.74%, 23.23%, and 16.96% of all detectable immunopositive tumour cells, respectively." (PMID 40981193, 2025). "Previous attempts to identify tumour cells employed molecular biological methods, including in situ hybridization, which pronounced diffuse cytoplasmic reactivity of FGF23 in the cytoplasm of neoplastic cells." (PMID 40981193, 2025). "Four months after surgery, both sodium phosphate and alphacalcidol were stopped and %TRP was normalized; however, serum ALP levels (280 U/L) and serum FGF23 levels (108.0 pg/mL) remained high, indicating the presence of residual tumor." (PMID 39866919, 2025). "If the tumor cannot be resected, novel therapeutic approaches include treatment with the anti-FGF23 antibody burosumab." (PMID 40611284, 2025).
tumor (continued). "One participant underwent surgery for Grisel's syndrome, and another for the removal of a FGF23‐producing tumour of the scapula." (PMID 40350717, 2025). "Early diagnosis and complete surgical removal of the FGF23-secreting tumor are crucial for reversing the disease." (PMID 39866529, 2025). "In contrast, colocalization with atypical FGF23-secreting cells was rare, indicating minimal direct effects on tumour cell activity." (PMID 40981193, 2025). "In NTera2 xenograft tumors, FGF23 was expressed in only 5–10% of tumor cells, which shows that the phenotype of the NTera2 cells changes in vivo." (PMID 40279260, 2025). "When used in a patient with metastatic TIO harboring a FN1-FGFR1 fusion, infigratinib was shown to profoundly lower FGF23 levels and reduce tumor burden, although the biochemical response reversed after drug discontinuation." (PMID 39755803, 2025). "A combination of systemic venous sampling and 68Ga-DOTATOC PET/CT was useful in detection of a small FGF23-producing tumor." (PMID 39866919, 2025). "This limitation also prevents FGF23 from being used as a reliable marker of disease progression or tumor growth while a patient is taking burosumab." (PMID 39755803, 2025). "MCs constituted a minor population related to the FGF23-secreting tumour, representing 0.23% of all tumour cells and 0.7% of all immunopositive cells in whole-section phenotyping." (PMID 40981193, 2025). "A combination of SVS and 68Ga-DOTATOC PET/CT was useful in the present case for detecting a small-sized FGF23-producing tumor." (PMID 39866919, 2025). "The combination of 68Ga-DOTATOC PET/CT and systemic venous sampling for FGF23 was a valuable method for localizing an FGF23-producing tumor, especially because the tumor was small." (PMID 39866919, 2025). "In our case, this latter highlighted the hypermetabolic lesion in the thigh, which turned out to be the tumor secreting FGF23." (PMID 39888445, 2025). "Unlike the majority of FGFs which bind to cells locally and have confined autocrine/paracrine activities, FGF23 synthesised by bone osteocytes and osteoblasts and by rare mesenchymal tumours enters the circulation and has hormonal actions." (PMID 38731904, 2024). "Here, we showed that, when comparing these three tumour types, FGF23 protein is expressed at high levels specifically in UPSb." (PMID 38397231, 2024). "Thediagnosis of FGF-23-producing tumor and osteomalacia was based on laboratory and imagingfindings and the onset of these described clinical manifestations at a late age1,2,3." (PMID 38913332, 2024). "While in TIO, removal of the FGF23-producing tumour is the primary therapy, neutralization of FGF23 in these patients, and particularly in patients with XLH, has become an important therapy modality and ameliorates many of the problems." (PMID 37660247, 2024). "Not only does FGF23 function in bone diseases, but it has also been found to promote tumor progression in various cancers." (PMID 39267764, 2024). "After establishing the diagnosis of TIO, the main challenge was to localize the FGF23-producing tumour." (PMID 38542041, 2024). "In 50 well-characterized phosphaturic mesenchymal tumours, excessive FGF23 production was attributable to a fibronectin (FN1)–FGFR1 fusion gene in 21 (42%) tumours and in 3 (6%) to a FN1-FGF1 fusion gene." (PMID 38731904, 2024). "FGF7 (keratinocyte growth factor KGF) was identified in tumours associated with TIO, and FGF7 and FGF23 were increased in blood draining the tumour site of a patient with TIO." (PMID 38731904, 2024). "Tumour-induced osteomalacia (TIO) is a rare paraneoplastic syndrome mediated by tumour overproduction of phosphaturic hormone fibroblast growth factor 23 (FGF23)." (PMID 39734682, 2024). "The Top 3 genes that were upregulated upon tumor growth were found to be Sprr1a (small proline-rich protein 1A, FC = 19.09, p < 0.01), Gal (Galanin, FC = 5.11, p < 0.0001) and FGF23 (fibroblast growth factor receptor 23, FC = 4.22, p < 0.001)." (PMID 37573456, 2023).
tumor (continued). "Only 12 cases reported the expression of FGF23 through immunostaining, mRNA expression, chromogenic in-situ hybridization, or Northern hybridization of FGF23 in tumors or tumor-derived cell lines." (PMID 37033241, 2023). "The phosphaturic hormone FGF-23, is usually elevated, and it usually decreases after complete resection of the tumor." (PMID 37623022, 2023). "This review aims to summarize the current knowledge about OC, FGF23, SCL, and LCN2 and to characterize the association between them and tumor bone metastasis." (PMID 36926025, 2023). "In this case report, we want to highlight the paramount importance of adequate tumor screening in adult patients with acquired hypophosphatemia, and the crucial lead that phosphate and vitamin D regulating hormones (FGF23) have for suspecting TIO." (PMID 35145798, 2022). "Tumor cells produce fibroblast growth factor 23 (FGF23) which in turn decreases proximal tubule reabsorption of phosphates and also inhibits vitamin D3 metabolism." (PMID 35204618, 2022). "After resecting the tumor, the serum FGF23 level started to decrease immediately and normalized within 3 hours." (PMID 36686800, 2022). "Tumor-induced osteomalacia (TIO) is a rare, acquired disease of renal phosphate wasting and disturbed vitamin D homeostasis as a result of the action of a phosphaturic protein – FGF-23, produced by a neoplasm." (PMID 35090436, 2022). "We found a positive correlation between FGF23 (xULN) and tumor size (r = 0.344, P < 0.001; N = 130)." (PMID 35857061, 2022). "Studies in the literature report that the removal of an FGF23-releasing tumor mass resolved muscular aches in a patient suffering from TIO, and the use of an antibody directed against FGF23 enhanced hand grip strength and spontaneous movement in the Hyp mouse." (PMID 36553684, 2022). "The FGF23 tumor tissue concentration was higher in E0771 tumors as compared to 4T1 and 67NR and was also higher in 4T1 tissue as compared to 67NR in the 5000 IU and 100 IU+cal groups." (PMID 36230508, 2022). "The pathogenesis of PMTs is still unclear and is primarily related to the abnormal tumor secretion of fibroblast growth factor 23 (FGF-23)." (PMID 36615052, 2022). "Definitive management of the tumor is with surgical resection and postoperative serial blood tests, including serum phosphate FGF-23 level." (PMID 34453276, 2021). "Tumor cells stained positive for FGF23, somatostatin receptor 2, and cluster of differentiation 56 but negative for h-caldesmon on immunohistochemistry." (PMID 34559137, 2021). "The tumor responsible for TIO produces fibroblast growth factor 23 (FGF-23) which plays a role in regulating renal handling of phosphate and 25-hydroxyvitamin D 1α-hydroxylase activity." (PMID 33833917, 2021). "FGF-23 levels are often increased in these patients and usually decrease after complete resection of the tumor." (PMID 34884774, 2021). "The AUC of the ROC curve for the FGF23 protein relating to differentiation in the clinical stage of the tumor and histopathological differentiation of the tumor are 0.54 and 0.62, respectively." (PMID 32570721, 2020). "Above all, the best cutoff values of phosphate and FGF23 presented limited sensitivity and specificity, which probably indicated that tumor location or surgical procedure were more important factors for outcomes." (PMID 31643101, 2020). "This is a rare paraneoplastic syndrome due to a tumor excessively producing FGF23, which, in line with its main endocrine effects, induces renal phosphate excretion, as well as reduction of 1,25(OH)2D3." (PMID 33520985, 2020). "High preoperative fibroblast growth factor 23 (FGF23) levels were also associated with refractory after adjusting for involving tissue and tumor malignancy." (PMID 31643101, 2020). "This review summarizes the current knowledge of the significance of FGF23 and αKlotho for tumor cell signaling, biology, and clinically relevant parameters in different forms of cancer." (PMID 33520985, 2020).